GDF15 (growth differentiation factor 15)
Diseases named in the same sentence as GDF15 in open-access papers (continued):
Sharing a sentence is not in itself a finding about the gene and the disease.
diabetes (continued). "Despite these efforts, our results suggest that GDF-15, in line with its low specificity, is more strongly associated with general clinical risk factors, especially diabetes and LDL cholesterol levels, than with specific indicators of atherosclerotic burden or cardiac dysfunction." (PMID 39780955, 2024). "In addition, GDF-15 predicts the risk of major adverse cardiovascular events in patients with diabetes, as reported by a meta-analysis involving nearly twenty thousand patients." (PMID 38828460, 2024). "GDF15, a member of the tumor growth factor superfamily, has recently been identified as a possible biomarker of aging and is associated with various clinical conditions, including coronary artery disease, diabetes, and various cancer types." (PMID 37860011, 2023). "The association of GDF-15 with physical performance, such as gait speed, has been shown in multiple studies, but no studies have specifically studied poor physical function in persons with diabetes." (PMID 37152099, 2023). "Future prospective longitudinal studies are required to evaluate the potential role of GDF-15 in screening persons with diabetes at risk of poor physical function and the impact of multidomain interventions in reducing the long-term risk of poor physical function." (PMID 37152099, 2023). "Our analyses also found that GDF15 plasma levels are a strong predictor of incident diabetes and an independent predictor of all-cause mortality, cardiovascular disease, and diabetes morbidity, suggesting its potential use as a pre-diabetic prognostic biomarker." (PMID 35916366, 2022). "In spite of limited direct evidence on GDF-15 in relation to gallstones, the associations of GDF-15 or gallstones, respectively, with diabetes indirectly support and enrich the hypothesis." (PMID 35769993, 2022). "It is possible that the increase in the plasma levels of GDF-15 in the patients with diabetes may cause a counter-regulatory and compensatory mechanism which protects against angiogenesis, but not sufficient to protect against DR." (PMID 33790859, 2021). "This may explain the association between GDF-15 and DR since DR is primarily caused by microvascular injury during diabetes." (PMID 33790859, 2021). "Serum GDF-15 was found to be associated with various complications of diabetes." (PMID 33312062, 2020). "After adjusted for basic clinical risk factors (age, sex, smoking hypertension, body mass index, diabetes mellitus and hyperlipidemia), in multivariate analysis, GDF-15 values > 1800 ng/L was associated with the incidence of MACEs with an HR of 1.74 (95% CI 1.44–2.02; P < 0.001)." (PMID 32746821, 2020). "To review the influence of the GDF-15 pathway on weight loss induced by metformin, we searched for the keywords “GDF-15”, “metformin”, “weight”, “diabetes drugs” alone, or in combination in the public databases of PubMed, Google Scholar, and ClinicalTrials.gov." (PMID 33312159, 2020). "The association between GDF-15 and diabetes tended to be less significant with increasing age." (PMID 30350239, 2019). "However, this evidence was inconclusive, whereas our results demonstrated that the longitudinal association between GDF-15 and diabetes remained significant even after adjustment." (PMID 30350239, 2019). "In this study, the sample size was fairly small (180 cases of diabetes and 372 control participants), and large cohort studies are still required to clarify whether circulating GDF-15 levels are associated with the incidence of diabetes." (PMID 30350239, 2019). "Further adjustment for CRP attenuated the association between GDF-15 quartiles and diabetes risk." (PMID 30350239, 2019). "GDF-15 may be useful for identification of people with a risk of incident diabetes, especially if those people are ≤60 years old." (PMID 30350239, 2019). "Our aim was to explore whether circulating levels of GDF-15 at baseline are positively associated with future diabetes incidence in a middle-aged urban population." (PMID 30350239, 2019).
diabetes (continued). "The risk of developing diabetes increased with increasing quartiles of GDF-15." (PMID 30350239, 2019). "It is logical to consider GDF-15 as a risk factor for thyroid cell proliferation in diabetes." (PMID 28489602, 2017). "The association between increased GDF-15 levels and diabetes has also been revealed." (PMID 27311391, 2016). "The association between elevated GDF-15 levels and diabetes has also been reported." (PMID 25171167, 2014). "At baseline there were independent associations between GDF-15 and current smoking, diabetes mellitus, biomarkers of cardiac (high-sensitivity troponin-T, NT-proBNP) and renal dysfunction (cystatin-C) and inflammatory activity (C-reactive protein), and previous cardiovascular disease (CVD)." (PMID 24312445, 2013). "Accumulating evidence indicates that GDF15 is associated with the development and prognosis of diabetes mellitus, while whether GDF15 can be induced by high glucose is unknown." (PMID 23799024, 2013). "Thus, GDF15 may in part influence or be influenced by certain cardiometabolic risk factors such as diabetes mellitus and A1C in both racial groups." (PMID 39668628, 2024). "This might affect the association with diabetes as metformin increases levels of GDF-15." (PMID 39780955, 2024). "However, the increase in GDF15 serum levels found in the rs1054564 variant carriers suggests that the impact of this SNP on diabetes and atherosclerosis may be due, at least partially, to the increase in GDF15 blood concentrations." (PMID 39596055, 2024). "In addition, low circulating GDF15 levels have been associated with pregnancy complications, including early pregnancy loss, preeclampsia and diabetes, while aberrantly high circulating GDF15 levels have been associated with an increased risk of hyperemesis gravidarum." (PMID 37272232, 2023). "Since LD patients are not only at risk for cardiovascular events and diabetes, but also have an increased morbidity and mortality due to other complications e.g., acute pancreatitis and liver failure, increased GDF15 levels might be a predictor for elevated overall morbidity and mortality in LD." (PMID 33003626, 2020). "GDF-15 is also an independent predictor of insulin resistance and abnormal glucose homeostasis in obese individuals, thereby it may provide a link between obesity, diabetes and cardiovascular risk." (PMID 33312062, 2020). "However, longitudinal data relating to the association between GDF-15 and diabetes risk are scarce." (PMID 30350239, 2019). "In non-diabetic individuals, GDF-15 could predict future impaired glucose control and insulin resistance, and in population free of clinically-overt cardiovascular disease, GDF-15 levels are positively associated with age, diabetes, hypertension, creatinine and NTproBNP levels." (PMID 27311391, 2016). "Additionally GDF-15 has been linked to hyperglycemia and diabetes mellitus (DM)." (PMID 27056183, 2016). "The consistent associations between the GDF-15 level and smoking, diabetes, and biomarkers of myocardial and renal dysfunction and inflammation suggested that expression of GDF-15 might be a shared and early indicator of cellular vulnerability to the development of vascular and cancer diseases." (PMID 24312445, 2013). "Patients with diabetes had significantly higher GDF15 than unaffected patients (1449 vs. 1117, P = 0.021)." (PMID 41016991, 2026). "GDF15 values statistically correlated with age, prevalence of diabetes, serum level of aspartate aminotransferase/γ-glutamyltransferase/creatinine/blood sugar/albumin, and PMI." (PMID 41016991, 2026). "Second, in terms of diabetes mellitus, it has been reported that circulating GDF15 levels are affected by type 2 diabetes mellitus and its systemic complications and metformin, one of its treatment medications." (PMID 40142684, 2025). "In the univariable model, age, sex, diabetes, hypertension, and metformin treatment were found to significantly affect circulating GDF15 levels." (PMID 40530451, 2025).
diabetes (continued). "Previous literature has reported GDF-15 as a biomarker in cardiovascular disease, kidney disease, liver disease, metabolic syndrome, diabetes mellitus, and sepsis." (PMID 40181460, 2025). "Comparison among the three groups showed that GDF-15 levels were highest in the DR group and increased progressively with diabetes severity." (PMID 41019919, 2025). "In fact, under conditions of cellular stress, such as in several diseases (especially in cancer, cardiovascular disease, obesity, diabetes, mitochondrial diseases, and aging), serum GDF15 levels are remarkably increased." (PMID 39825925, 2025). "This study provides valuable insights into the role of macrophage depletion in combating diabetes-accelerated kidney senescence through modulation of the GDF-15 and Klotho signaling pathways." (PMID 40362229, 2025). "For example, GDF15 is known to inhibit islet inflammation, oxidative stress and β cell apoptosis, thereby reducing the occurrence and development of diabetes." (PMID 41290610, 2025). "The association with GDF-15 was persistent after correction for the confounders age, GFR, atrial fibrillation, and diabetes (r = 0.685, p = 0.029) and with sST2 (r = −0.709, p = 0.022)." (PMID 40869494, 2025). "Among patients with diabetes, GDF15 levels were further elevated in those with presence of microvascular complications or HbA1c > 7%." (PMID 40019842, 2025). "The positive association between diabetes and risk of hospitalization or death was mediated 26.7% by TNFR1, 8.3% by IL-6, and 81.6% by GDF15." (PMID 41280118, 2025). "GDF15 expression is notably downregulated under hyperglycemic conditions, which are characteristic of diabetes mellitus, suggesting a link between metabolic dysregulation and bladder cancer progression." (PMID 41009692, 2025). "GDF15 also appears related to cardiac function in children with other systemic conditions including diabetes and cardiac arrest." (PMID 40019842, 2025). "The purpose of this study is to explore the association between serum growth differentiation factor 15 (GDF15) and metabolic syndrome (MS), as well as its components in patients with Type 2 diabetes mellitus (T2DM)." (PMID 41497484, 2025). "A longer duration of diabetes was associated with higher QRISK and plasma GDF-15 levels at baseline." (PMID 40699839, 2025). "Two studies describe higher GDF15 in patients with Type 1 Diabetes Mellitus (T1DM) compared to controls." (PMID 40019842, 2025). "Despite these findings, the interplay between the five indices derived from cystatin C and creatinine and GDF‐15 remains poorly understood, particularly in individuals with diabetes mellitus." (PMID 40700030, 2025). "GDF15 has emerged as a promising therapeutic candidate for type 2 diabetes mellitus (T2DM), largely due to its impact on glucose metabolism, insulin sensitivity, and weight regulation." (PMID 40837873, 2025). "Given that both DN and DR are microvascular complications of diabetes, a positive correlation between GDF-15 and DR has also been reported." (PMID 41019919, 2025). "Diabetes, CVD, COPD, and cancer were the conditions significantly associated with higher GDF-15 levels (p<0.0001 for the three comparisons)." (PMID 38686386, 2024). "These beneficial metabolic effects provide new insights into GDF-15 as a potential target for diabetes treatment." (PMID 38672115, 2024). "In humans, plasma concentration of GDF15 increases with factors such as age, smoking, drug consumption, and in response to metabolic stress like diabetes." (PMID 38892145, 2024). "In the case of GDF-15, patients with levels above 1213.9 ng/mL were older on average (58.5 years vs. 52.5 years, p < 0.01), had a higher incidence of diabetes (25.4% vs. 6.2%, p < 0.01), and a higher BMI (28.7 kg/m2 vs. 26.7 kg/m2, p = 0.04)." (PMID 39334904, 2024). "Among other more-expressed proteins in patients with diabetes are CES1, GDF15, and GUSB proteins, which were previously associated to T2D." (PMID 38732002, 2024).
diabetes (continued). "A predictive model involving high GDF-15 levels, diabetes status, and advanced age was constructed, and the ROC curve showed that the predictive model had good value in predicting the risk of cardiotoxicity, with an AUC of 0.885 (95% CI: 0.774–0.997)." (PMID 38828460, 2024). "Under normal conditions, human serum GDF-15 levels are low but are significantly elevated in various diseases, including malignancies, CVDs, renal disorders, and diabetes." (PMID 38672115, 2024). "Despite all this, the levels of FGF-21 and GDF-15 are likely influenced by age, body max index (BMI) and some certain diseases (e.g. heart failure, myocardial infarction, pulmonary hypertension, diabetes, metabolic syndrome, autoimmune diseases, and cancer)." (PMID 36935492, 2023). "GDF15 is a cytokine from the TGF-β superfamily associated with hyperglycemia and risk of incident diabetes." (PMID 36528847, 2023). "Compared to the plasma GDF15 level, the urinary GDF15-creatinine ratio is less dependent on renal function and sensitively fluctuates with diabetes and statin treatment." (PMID 37532799, 2023). "In the samples of 2081patients with NSTE-ACS, increasing levels of GDF-15 at admission were positivelyassociated with age, female sex, hypertension, and diabetes." (PMID 39077481, 2023). "In contrast, GDF15 expression increases under pathological or stress conditions including diabetes, smoking, surgery, exercise, cancer, non‐alcoholic fatty liver disease (NAFLD), cardiovascular and kidney diseases, as well as in mitochondrial disease." (PMID 36992609, 2023). "Our preclinical findings support clinical studies on individuals with diabetes receiving metformin treatment to evaluate how beverage selection affects body weight, glycemic control, and GDF15 levels." (PMID 37299435, 2023). "Between these extremes, we find GDF15 to be greatly enriched in the RHAPSODY proteomics analysis, having high association scores for multiple diabetes types and medium-high text mining scores and novelty." (PMID 37590326, 2023). "There was no statically significant difference in baseline data such as age, sex, diabetes, hypertension, and coronary heart disease between GDF-15 <1,200 pg/ml group and GDF-15 ≥1,200 pg/ml group." (PMID 37288264, 2023). "Plasma levels of GDF15, a member of the transforming growth factor‐β superfamily, are increased in diabetes, cardiovascular disease, chronic inflammatory diseases, and NAFLD." (PMID 35510313, 2022). "Over-activated GDF15 in experimental diabetes inhibits the progression of inflammatory reaction through inhibition of NLRP3 inflammasome." (PMID 36140453, 2022). "Higher expression of the GDF15 in diabetes mellitus plays a crucial role in the attenuation of inflammatory and metabolic complications." (PMID 36140453, 2022). "We found that compared with baseline levels, serum GDF15 levels increased about 35% after a 12-week metformin treatment in patients with type 2 diabetes mellitus." (PMID 36273168, 2022). "Serum GDF15 levels were significantly elevated after metformin treatment in patients with type 2 diabetes mellitus." (PMID 36273168, 2022). "Inflammation, which is also a hallmark of chronic anemia, increases the expression of GDF-15 in several pathologies such as ESKD, cancers, diabetes and cardiovascular diseases." (PMID 35251002, 2022). "A high expression of GDF-15 has been proposed to be a predicting factor and a potential treatment target for diabetes mellitus along with complications." (PMID 35769993, 2022). "Previous studies found that GDF15 was closely related to diabetes mellitus, while GDF15 was newly discovered to be a promising target of metformin." (PMID 36273168, 2022). "Systemic GDF15 was characterized as an excellent predictive marker for hepatic fibrosis as well as type 2 diabetes mellitus." (PMID 36430499, 2022). "The study was aimed to investigate the relationship between GDF15 and glycemic control after metformin treatment in patients with type 2 diabetes mellitus." (PMID 36273168, 2022).
diabetes (continued). "Targeting of GDF15 signaling has already been considered in the context of other diseases, such as diabetes and cancer." (PMID 35993367, 2022). "Due to its many functions, GDF15 has been a target of pharmacological research to treat, e.g., cachexia and diabetes." (PMID 36235718, 2022). "Among women with diabetes, BMI before pregnancy was negatively correlated with NT-proBNP (rs = − 0.261, p = 0.005) and GDF-15 (rs = − 0.241, p = 0.010)." (PMID 35796791, 2022). "There still remains a paucity of information on the relationship between GDF15 and the glucose-lowering effect of metformin in patients with type 2 diabetes mellitus." (PMID 36273168, 2022). "Although these cross-sectional studies have focused on GDF15 and metformin, our study first investigated the change of serum GDF15 levels before and after metformin treatment in patients with type 2 diabetes mellitus." (PMID 36273168, 2022). "High circulating GDF-15 levels showed a significant correlation with a faster decline of renal function in patients with diabetes mellitus type 1, IgA nephropathy, and CKD stages 1–4, suggesting its possible relevance as a marker of progression in ccRCC." (PMID 34943605, 2021). "Several inflammatory cytokines, such as IL-1β, IL-2, and TNF-α, increase GDF15 expression, and thereby circulating GDF15 levels are elevated in diabetes and cardiovascular diseases." (PMID 34944728, 2021). "Several biomarkers of diabetes mellitus have been reported, such as GDF-15, YKL-40, 2-aminoadipic acid, serum adipocyte fatty acid–binding protein, and urinary 8-oxo-7,8-dihydro-2′-deoxyguanosine." (PMID 34603195, 2021). "In females, diabetes was associated with elevated GDF-15 and MMP-9, whilst males with diabetes only had elevated GDF-15." (PMID 34526107, 2021). "Concerning the mitochondrial metabolism, a positive relationship between GDF15 and type 2 diabetes mellitus (T2DM) has been shown." (PMID 34445593, 2021). "In contrast, genetic deletion of GDF-15 aggravated tubular and interstitial injury, which resulted in glycosuria and polyuria in mice with diabetes." (PMID 34706669, 2021). "The top 5 proteins we identified (GDF15, GAL4, IL1RT1, CTSD and SELE) are robustly associated with diabetes in a variety of studies, consistent with our findings." (PMID 34372849, 2021). "As GDF-15 measurements can be affected by systemic diseases such as diabetes and COPD, patients with these diseases were excluded." (PMID 34048486, 2021). "At baseline, plasma GDF-15 was higher in longer diabetes duration (1.19 ± 0.14 vs. 0.82 ± 0.09 ng/mL, p = 0.034), as was the QRISK (22.8 ± 2.6 vs. 15.3 ± 3.4%, p = 0.031)." (PMID 33925808, 2021). "Nevertheless, most previous related studies have focused on circulating GDF15 levels and myocardial or coronary artery diseases in patients with diabetes, and the relationship between GDF15 and LEAD has been less explored." (PMID 32222153, 2020). "The variables significantly associated with AF recurrence included age, persistent AF, diabetes mellitus, NT-proBNP, LAD, LAAV, ablative strategy (CPVI-only), and baseline GDF-15." (PMID 32904560, 2020). "The present study aimed to explore the association between GDF15 and LEAD in Chinese patients with type 2 diabetes mellitus (T2DM)." (PMID 32222153, 2020). "GDF15 has been reported to be protective toward chronic complications that arise from old age or diabetes." (PMID 32671100, 2020). "There are no more studies concerning GDF-15 and microvascular disease in diabetes mellitus, but it is very possible that vascular inflammation results in increased GDF-15 production, which is revealed in the current study." (PMID 31936869, 2020). "Participants who developed diabetes during follow-up had higher baseline GDF-15 levels than participants who were free of diabetes at the end of follow-up (p < 0.001, data not shown)." (PMID 30350239, 2019).